MIR372 (microRNA 372)
Synonyms: hsa-mir-372; MIRN372
Gene: MicroRNA gene on chromosome 19 (53,787,890 to 53,787,956, forward strand). Ensembl gene ENSG00000199095.
Gene Ontology:
Biological process: miRNA-mediated post-transcriptional gene silencing
Homologues: Orthologues: chimpanzee ptr-mir-372 (100% identical), macaque mml-mir-372 (97% identical), rat rno-mir-295-1 (72% identical), rabbit ocu-mir-373 (64% identical), mouse Mir294 (63% identical), mouse Mir291b (58% identical), dog MIR371 (55% identical). Paralogues in human: MIR371A (73% identical).
Diseases named in the same sentence as MIR372 in open-access papers:
MIR372 is named in the same sentence as 1 disease in open-access papers, as found by Europe PMC text mining. Sharing a sentence is not in itself a finding about the gene and the disease.
MIR372 shares sentences with these, for which no sentence is quoted: tumours (1 paper).